NLRP3 (NLR family pyrin domain containing 3)
Diseases named in the same sentence as NLRP3 in open-access papers (continued):
Sharing a sentence is not in itself a finding about the gene and the disease.
Sepsis (continued). "In view of the fact that increasing evidence demonstrates the mechanism of metabolism reprogramming regulating NLRP3 activation in macrophages, the key enzymes and metabolites participated in this regulation should be clearer for better interpreting the relationship of NLRP3 inflammasome and sepsis." (PMID 35847986, 2022). "Furthermore, inhibition of the NLRP3 inflammasome protects against sepsis-induced cardiomyopathy." (PMID 36619743, 2022). "Likewise, NLRP3/IL-1β inflammasome pathway inhibition attenuates cardiac atrophy in sepsis." (PMID 36359339, 2022). "However, whether HSF1 affects the NLRP3 inflammasome activation during sepsis-induced ALI and its molecular mechanisms remains unknown." (PMID 35720321, 2022). "Thus, downregulation of NLRP3 and NF-κB P65 expressions with simultaneous inhibition of proinflammatory cytokines could effectively improve heart function in the sepsis model." (PMID 35672697, 2022). "Moreover, changes in cellular glucose metabolism pathways, such as in the key enzymes and intermediates, could impact the progression of sepsis by regulating NLRP3 inflammasome activation, multi-inflammatory factor release, and others." (PMID 35847986, 2022). "In addition to the NLRP3 inflammasome, key enzymes and metabolic intermediates of cellular glucose metabolism also affect macrophage function through a variety of molecular mechanisms, thus contributing to the occurrence and development of sepsis." (PMID 35847986, 2022). "Thus, arguably, systemic-inflammatory-response syndrome (SIRS) and sepsis could be differentiated by the measurement of IL-31, IL-1ß, and NLRP3." (PMID 35742951, 2022). "Furthermore, we observed that when exogenous HNP-1 was intraperitoneally administered into Nlrp3−/− and Casp1−/− mice 6 hours after sepsis, the survival of mice administered a high dose of HNP-1 was comparable to that of mice administered a low dose of HNP-1 or PBS." (PMID 35935811, 2022). "Moreover, the inactivated NLRP3 inflammasome due to melatonin could ameliorate sepsis-induced heart injury." (PMID 35508474, 2022). "However, further studies are warranted to understand the molecular details of how RNH1 regulates the priming and activation signal of the NLRP3 inflammasome and how these mechanisms are dysregulated in human inflammatory diseases, including COVID-19 and sepsis." (PMID 35256513, 2022). "Whether NETs in sepsis promote the activation of the platelet NLRP3 inflammasome is unknown." (PMID 35563812, 2022). "Additionally, repression of the NLRP3/IL-1β axis may exert protection against endothelial relaxation dysfunction induced by sepsis." (PMID 35508474, 2022). "NLRP3 inflammasome, a typical Nod-like receptor, is also an important PRR in sepsis, and it has been reported that exosomes released from LPS-treated macrophages could induce NLRP3 inflammasome and caspase-1 activates and induces the release of the proinflammatory factor IL-1β." (PMID 35326456, 2022). "Although the currently available data on the role of NLRP3 on septic cardiomyopathy are informative for a younger age, further studies on mature (12‐month‐old) and aged mice (24‐month‐old) are needed to provide data that are more translatable to aged patients with sepsis." (PMID 34472725, 2021). "Furthermore, we analyzed whether p47phox was functionally involved in ROS production and triggered NLRP3 inflammasome activity in the function of GPR43 on sepsis-induced inflammatory reactions." (PMID 34584017, 2021). "Because Nlrp3 deletion reduces mortality and sepsis-induced end-organ damage, such as muscle failure, cardiomyopathy and acute lung injury, pharmacological NLRP3 inhibition might be beneficial in sepsis." (PMID 34572540, 2021). "Recent evidence demonstrates that NLRP3/IL-1β activation is associated with the severity of SAE and that inhibiting the adverse effects of NLRP3 inflammasomes may be a good strategy to avoid excessive inflammation during sepsis." (PMID 34062710, 2021).
Sepsis (continued). "Pharmacological inhibition of NLRP3 might therefore be beneficial in sepsis." (PMID 34472725, 2021). "Indeed, NLRP3 Inflammasome is known for regulation of inflammation in sepsis model, but whether GPR43 regulates NLRP3 Inflammasome remains unclear." (PMID 34584017, 2021). "In addition, binding of TMEM173 (also known as stimulator of interferon gene) with type-I interferons regulatory factor 3 under LPS stimulation could increase NLRP3 expression, promote pyroptosis, and aggravate sepsis mediated myocardial injury." (PMID 34305952, 2021). "In consistent with previous observation of PKM2-HIF-1α metabolic pathway that promote AIM and NLRP3 inflammasome activation, the HIF-1α-mediated anaerobic glycolysis upregulated after depletion of neurotransmitter-mediated immune responses showed association with sepsis lethality." (PMID 34824200, 2021). "And in this study, we observed severe pyroptosis and serious damage of the liver in septicemia-related liver injury in CD38-deficient mice, whereas both pyroptosis and damage of the liver can be significantly reversed in TLR4 mutant mice, accompanied by the decrease in NLRP3 and GSDMD." (PMID 33860064, 2021). "Moreover, the definition of GRP43 as mitochondrial damage sensed NLRP3 inflammasome may provide insights to the development of therapeutics for sepsis or inflammatory diseases such as rheumatism, carditis and so on." (PMID 34584017, 2021). "Several sepsis studies investigate the interaction of melatonin with NLRP3 in mouse hearts, where sepsis activates the NLRP3 inflammasome and melatonin injection suppresses this activity, confirmed by a decrease in the levels of mature caspase-1 and IL-1β, NLRP3, and ASC." (PMID 34202842, 2021). "The entire process of NLRP3 inflammasome activation requires participation of both priming and triggering signals, so their inhibitions may be beneficial for controlling the inflammation response in sepsis." (PMID 33324236, 2020). "However, the mechanism of regulation of the NLRP3 inflammasome in sepsis has remained unclear." (PMID 33182702, 2020). "Since the deficiency of NLRP3-IL-1β pathway prevented chronic, but not acute, neuroinflammation after sepsis, we next studied whether blockage of generation or action of IL-1β would avoid sepsis-associated neurodegeneration once acute neuroinflammation began." (PMID 32070376, 2020). "Furthermore, inhibition of the NLRP3 signalling pathway protects against sepsis-induced AKI." (PMID 32131850, 2020). "Reactive oxygen species (ROS) are triggered by energy metabolism and respiratory dysfunction in sepsis, which not only cause oxidative damage to tissues and organelles, but also directly and indirectly promote NOD-, LRR-, and pyrin domain-containing protein 3 (NLRP3) inflammasome activation." (PMID 33324236, 2020). "Thus, by showing the protective effects of acetate in LPS-induced endotoxemia and the NLRP3 inflammasome-dependent peritonitis model, the present study may serve as the basis for more extensive research on acetate in sepsis and other inflammatory diseases." (PMID 31337751, 2019). "Therefore, the pharmacological inhibition of the NLRP3 pathway might constitute a potent protective strategy during sepsis." (PMID 30779706, 2019). "Therefore, further research is needed into how the P2X7 receptor controls NLRP3 inflammasome in sepsis, and whether these proinflammatory pathways can participate in the immunosuppression that occurs in human sepsis." (PMID 31221993, 2019). "However, it is still not known whether, and in what way, the interrelationship between GAPDH and NLRP3 contributes to protection against pathogens or plays an important role in sepsis." (PMID 31403210, 2019). "Together, our findings establish ethyl pyruvate as a novel NLRP3 inhibitor and unravel the mechanisms by which this metabolite derivative exerts anti-inflammatory effect in various types of diseases or illnesses, such as sepsis, alcoholic liver injury, and acute kidney injury." (PMID 30134814, 2018).
Sepsis (continued). "Therefore, CO may also inhibit NLRP3 inflammasome activation by increasing NO levels in sepsis-induced AKI." (PMID 26334271, 2015). "The aim of the present study is to evaluate whether sepsis activates NLRP3 inflammasome/caspase-1/IL-1β pathway in cardiac fibroblasts (CFs) and whether this cytokine can subsequently impact the function of cardiomyocytes (cardiac fibroblast-myocyte cross-talk)." (PMID 25216263, 2014). "In sepsis, GITR enhances the uptake of lysolipid phosphates by macrophages and specifically amplifies macrophage pyroptosis mediated by the NLRP3 inflammasome." (PMID 41513612, 2026). "In sepsis-induced acute lung injury, phosphorylated STAT3 recruits EP300, promoting acetylation of the histone region of the NLRP3 gene and thereby facilitating pyroptosis." (PMID 41513612, 2026). "To explore the molecular mechanism by which ECG improves sepsis-induced ALI, we evaluated the impact of ECG intervention on NLRP3 signaling transduction." (PMID 41496909, 2025). "For example, in sepsis, a positive feedback loop is formed between the HMGB1—TLR4 axis and the NLRP3 inflammasome, which amplifies the pro—inflammatory response." (PMID 40877572, 2025). "Mechanistically, PVT1 functions as a sponge for miR-20a-5p, which directly targets NLRP3, suggesting that PVT1 promotes cellular juxtaposition through the miR-20a-5p/NLRP3 signaling pathway, thereby exacerbating sepsis-induced AKI." (PMID 40657645, 2025). "Research has found that PPARG can reduce pyroptosis and liver damage during sepsis by inhibiting ROS levels and suppressing the TXNIP/NLRP3 signaling pathway." (PMID 40070882, 2025). "They confirmed that CircMAPK1 exacerbates sepsis-induced lung injury by destabilizing KDM2B mRNA to suppress WNK1 expression, thus facilitating NLRP3-driven macrophage pyroptosis." (PMID 40458798, 2025). "Overall, CDDO-Im alleviates NLRP3 inflammasome activation and HMGB1 release through the Nrf2 pathway, thereby activating mitophagy in sepsis-related ARDS." (PMID 40599023, 2025). "Simultaneous blockade of the HMGB1—TLR4 axis (e.g., via neutralizing antibodies) and the NLRP3 inflammasome (e.g., using MCC950) can decrease the secretion of IL—1β in experimental sepsis models." (PMID 40877572, 2025). "Here, we extend those findings by demonstrating that cilastatin also protects against sepsis-induced AKI via interference with the TLR4/MyD88/NF-κB and NLRP3 signaling pathways, resulting in improved survival." (PMID 40869248, 2025). "Notable candidates include MCC950, a selective NLRP3 inhibitor; anti–IL-1β monoclonal antibodies; and emerging GSDMD inhibitors, all of which aim to suppress the hyperinflammatory milieu of sepsis." (PMID 40558557, 2025). "In sepsis-induced myocardial injury models, H2S downregulates TLR4 and NLRP3 protein expression, inhibits MyD88-NF-κB signaling activation to reduce cytokine secretion, and blocks NLRP3 inflammasome assembly and IL-1β processing." (PMID 41277967, 2025). "Among the various inflammasome complexes identified, the NLRP3 inflammasome (NOD-like receptor family pyrin domain-containing 3) is the most extensively studied and clinically significant in the context of sepsis." (PMID 40558557, 2025). "Inhibition of NLRP3/ASC/Caspase-1 mediated pyroptosis-related signaling pathway, thus improving sepsis-related ALI." (PMID 40918090, 2025). "IL-38 guards against sepsis by inhibiting CD8+T cell apoptosis and NOD-like receptor protein 3 (NLRP3) activation." (PMID 40461967, 2025). "Complementarily, in sepsis-induced kidney injury, the OIP5-AS1/miR-186-5p/NLRP3 axis enhances NLRP3 inflammasome activation, linking OIP5-AS1 to innate inflammation and acute tubular damage." (PMID 41303683, 2025). "ROS-mediated NLRP3 activation has been observed in platelets from patients with Crohn’s disease, immune thrombocytopenic purpura (ITP) or sepsis." (PMID 40710328, 2025).
Sepsis (continued). "In addition, the system showed significant potential in reducing ROS production, suppressing NLRP3 expression, decreasing cardiomyocyte apoptosis, and improving survival in the sepsis model, illustrating the promising therapeutic effects of MSNs in sepsis‐related myocardial injury." (PMID 40599085, 2025). "Studies on the pathophysiology of pyroptosis in sepsis have mainly focused on the GSDMD and NLRP3-mediated signaling pathways." (PMID 40458798, 2025). "In a similar manner, our findings indicated that the downregulation of klotho following sepsis was ameliorated by CLM, resulting in the inactivation of NLRP-3." (PMID 40770673, 2025). "However, the regulatory mechanism of ATG16L1 on NLRP3 and its role in sepsis remain unclear." (PMID 40211890, 2025). "We subsequently sought to identify key pro-inflammatory mediators involved in sepsis, including TNF-α, IL-6, and the NLRP3 and RAGE signalling pathways." (PMID 41315622, 2025). "In a related study on sepsis induced by lipopolysaccharides (LPS), treatment with CAP was found to increase protein levels of caspase-1, ASC, and NLRP3, as well as the number of PI-positive cells, indicating activation of pyroptosis and apoptosis." (PMID 41226458, 2025). "The protective role of BA as an NLRP3 inflammasome inhibitor in SALI was subsequently established, and its potential therapeutic effect on sepsis was highlighted." (PMID 39887250, 2025). "Studies have reported that calycosin can relive sepsis-induced acute lung injury (ALI) by inhibiting the HMGB1/myeloid differentiation factor 88 (MyD88)/NF-κB pathway and activating the NLRP3 inflammasome." (PMID 41463300, 2025). "Taken together, these results demonstrate that emodin protects against LPS-induced sepsis by promoting FUNDC1-dependent mitophagy, thereby suppressing NLRP3 inflammasome activation and mitigating the ensuing inflammatory response in mice." (PMID 40520006, 2025). "Redox modifications regulate pyroptosis: The SSG of NLRP3 at Cys483 inhibits inflammasome activation, while thioredoxin (TRX)-1 reduces NLRP3 cysteine reactivity, attenuating sepsis-induced pyroptosis." (PMID 40927693, 2025). "In IRI and sepsis-induced AKI, ATP can activate NLRP3 inflammasome by binding to P2X7R, promoting the production of proinflammatory factors including IL-1β, IL-6, and MCP1 and impairing the kidney." (PMID 40709185, 2025). "Recent studies reveal that during acute inflammation or infection, calprotectin released from neutrophils enhances pyroptosis via the TLR4/NLRP3/caspase-1/GSDMD pathway, contributing to platelet death in sepsis." (PMID 40710328, 2025). "Literature validation yielded 30 ultra-high confidence therapeutic candidates, including both established sepsis genes (IL10, TREM1, S100A9, NLRP3) and novel targets warranting investigation." (PMID 41071041, 2025). "and demonstrates anti-inflammatory properties by reducing pro-inflammatory cytokines, inhibiting NLRP3 inflammasome activation, and blocking TLR4/NF-κB signaling in various pathological contexts (e.g., sepsis, hyperhomocysteinemia)." (PMID 41277967, 2025). "ADAR1 was downregulated in PMBCs of patients with sepsis, and overexpression of ADAR1 alleviated CLP-induced lung injury and NLRP3 inflammasome activation." (PMID 38169584, 2024). "In terms of the mechanism by which ACSS2 contributed to the induction of RTEC injury by sepsis, we demonstrated that ACSS2 regulates NLRP3-mediated caspase-1 activation and pyroptosis through the KLF5/NF-κB pathway." (PMID 38515158, 2024). "In the sepsis mouse model, the activation of the PERK/ATF4/CHOP signaling pathway trigger NLRP3/caspase-1-mediated pyroptosis and the generation of pro-inflammatory cytokines, leading to elevated mortality rates among septic mice." (PMID 38434710, 2024). "For instance, metformin inhibits NLRP3‐mediated macrophage pyroptosis through the AMP‐activated protein kinase (AMPK) pathway, thereby mitigating the inflammatory response in sepsis‐related lung injury." (PMID 39623879, 2024).
Sepsis (continued). "In sepsis, suppression of the E3 ubiquitin ligase SKP2 activates the NLRP3 inflammasome by attenuating the level of ubiquitination modification of NLRP3." (PMID 38698431, 2024). "In sepsis, the suppression of HSPA8 mediates the activation of NLRP3 inflammasome by attenuating ubiquitination modification level of NLRP3." (PMID 38698431, 2024). "This study lies in its contribution to the nuanced understanding of the molecular interactions in sepsis, and circMAPK1/KDM2B/WNK1/NLRP3 axis was identified as a promising target for the targeted therapeutic strategy of sepsis-induced ALI." (PMID 39300342, 2024). "In summary, our study revealed one of the essential and original mechanisms by which YOD1 promoted sepsis-induced DIC, and proposed YOD1 as a priming therapeutic target for NLRP3-inflammasome dysregulation-mediated disorders." (PMID 38789414, 2024). "RG100204 reduced cardiac and renal dysfunction, decreased activation of the NLRP3 inflammasome pathway and reduced myeloperoxidase activity in lung tissue, suggesting that AQP9 is a potential drug target for polymicrobial sepsis." (PMID 39544938, 2024). "In sepsis, down-regulation of HSPA8 mediates the occurrence of AECs pyroptosis by activating the NLRP3 inflammasome." (PMID 38698431, 2024). "Their research focused on the protective effects of tangeretin (TAN) on sepsis-induced ALI and its regulatory mechanism on NLRP3 inflammasomes." (PMID 38675431, 2024). "Recent evidence suggests that pyroptosis mediated by NLRP3(NOD-, LRR- and pyrin domain-containing 3) inflammasome activation plays a key role in sepsis." (PMID 38698431, 2024). "CircMAPK1 exacerbates sepsis-induced lung injury by destabilizing KDM2B mRNA to suppress WNK1 expression, thus facilitating NLRP3-driven macrophage pyroptosis." (PMID 39300342, 2024). "Our research adds to this understanding, showing that circMAPK1 was upregulated in sepsis patients and exacerbates lung injury, primarily regulated NLRP3-mediated macrophage pyroptosis via UPF1/KDM2B/WNK1/NLRP3 pathway." (PMID 39300342, 2024). "In sepsis, mitochondrial aldehyde dehydrogenase 2 (ALDH2) promotes the activation of NLRP3 inflammasome and participates in the occurrence of pyroptosis." (PMID 38698431, 2024). "Clinical samples and CLP mouse models both showed downregulation of ADAR1 in sepsis, and overexpression of ADAR1 significantly alleviated lung injury from CLP and reduced the activation of the NLRP3 inflammasome in pulmonary macrophages." (PMID 38169584, 2024). "Several clinical studies have indicated elevated levels of NLRP3, GSDMD, IL-1β, and IL-18 in sepsis patients." (PMID 39544947, 2024). "Ada-1 also attenuated sepsis-induced brain injury by regulating NOD-, LRR-, and pyrin domain-containing protein 3 (NLRP3) inflammasome activation." (PMID 39290715, 2024). "In the case of bacterial induced sepsis patients, a possible activation of the NLRP3 inflammasome pathway, which has been shown to be involved in the effect of S100A12 on the pathogenesis of sepsis-induced ARDS, was revealed." (PMID 36979757, 2023). "Our results showed that PHB1 was negatively correlated with the severity of sepsis patients, and the expression of PHB1 was also negatively correlated with the expression of NLRP3 inflammasomes." (PMID 37359543, 2023). "Inhibition of the NLRP3 inflammasome and activation of autophagy have shown promise as potential therapeutic targets for ARDS in sepsis patients." (PMID 37649483, 2023). "Therefore, modulating NF-kB/NLRP3 axis may be a key strategy for the treatment of sepsis." (PMID 37062835, 2023). "Previous clinical studies have reported elevated levels of NLRP3, GSDMD, IL-1β, and IL-18 in patients with sepsis." (PMID 38161332, 2023). "According to our findings, NLRP3, cleaved Caspase1, and ASC were upregulated in sepsis-induced AKI, which were similar to previous studies." (PMID 36632449, 2023).